KCNIP1 (potassium voltage-gated channel interacting protein 1)
Description:
Regulatory subunit of Kv4/D (Shal)-type voltage-gated rapidly inactivating A-type potassium channels. Regulates channel density, inactivation kinetics and rate of recovery from inactivation in a calcium-dependent and isoform-specific manner. In vitro, modulates KCND1/Kv4.1 and KCND2/Kv4.2 currents. Increases the presence of KCND2 at the cell surface.
Synonyms: KChIP1; VABP
Tractability: Small molecule: it has a binding pocket of medium quality. Antibody: UniProt places it where antibodies can reach, with high confidence; its Gene Ontology location is reachable by antibodies, with high confidence. PROTAC: its protein half-life has been measured.
Gene: Protein-coding gene on chromosome 5 (170,353,487 to 170,736,632, forward strand). Ensembl gene ENSG00000182132.
Subcellular location: Cell membrane; Cytoplasm; Cell projection, dendrite
Subcellular location (Human Protein Atlas): Vesicles
Pathways (Reactome):
Muscle contraction: Phase 1 - inactivation of fast Na+ channels
Gene Ontology:
Molecular function: calcium ion binding; potassium channel regulator activity; protein binding; transmembrane transporter binding
Biological process: regulation of potassium ion transmembrane transport; chemical synaptic transmission; membrane repolarization; muscle contraction; potassium ion export across plasma membrane; regulation of heart contraction; regulation of signal transduction
Cellular component: cytoplasm; cytoplasmic side of plasma membrane; Kv4.3-KChIP1 channel complex; plasma membrane; voltage-gated potassium channel complex; dendrite; synapse
Genetic constraint (gnomAD): Loss-of-function variants: 9 observed, 21.04 expected, observed/expected ratio (o/e) 0.43, 90% interval 0.26 to 0.75. The upper end of that interval is the gene's LOEUF score, 0.75, which puts it in group 3 of 6, group 1 being the genes least tolerant of losing a copy. Missense variants: 168 observed, 199.16 expected, observed/expected ratio (o/e) 0.84, 90% interval 0.74 to 0.96. Synonymous variants: 67 observed, 77.78 expected, observed/expected ratio (o/e) 0.86, 90% interval 0.71 to 1.06.
Homologues: Orthologues: chimpanzee KCNIP1 (100% identical), guinea pig KCNIP1 (98% identical), rat Kcnip1 (92% identical), mouse Kcnip1 (91% identical), rabbit KCNIP1 (91% identical), dog KCNIP1 (90% identical), pig KCNIP1 (90% identical), tropical clawed frog kcnip1 (89% identical), macaque KCNIP1 (88% identical), zebrafish kcnip1b (77% identical), zebrafish KCNIP1 (76% identical), Drosophila melanogaster CG5890 (49% identical), and 3 more. Paralogues in human: KCNIP4 (70% identical), KCNIP2 (66% identical), KCNIP3 (65% identical), NCS1 (39% identical), VSNL1 (38% identical), HPCA (37% identical), HPCAL1 (37% identical), HPCAL4 (36% identical), NCALD (35% identical), GUCA1B (29% identical), RCVRN (29% identical), GUCA1A (28% identical), and 2 more.
Diseases named in the same sentence as KCNIP1 in open-access papers:
KCNIP1 is named in the same sentence as 22 diseases in open-access papers, as found by Europe PMC text mining. Sharing a sentence is not in itself a finding about the gene and the disease. The quoted sentences say what the papers report.
epilepsy (4 papers, 2017 to 2023). A brain disorder characterized by episodes of abnormally increased neuronal discharge resulting in transient episodes of sensory or motor neurological dysfunction, or psychic dysfunction. "We also identified five potentially pathologic variants in genes associated with cardiac arrhythmia, including KCNMB1, KCNIP1, DPP6, JUP, F2, and TUBA3D that were identified in SUDEP patients but not present in our living epilepsy cases." (PMID 29619247, 2018).
Anxiety (3 papers, 2010 to 2025). Intense feelings of nervousness, tension, or panic often arise in response to interpersonal stresses. "KCNIP1 knockout mice also exhibited increased susceptibility to seizures, as demonstrated by enhanced anxiety-like behavior and altered GABAergic neurotransmission." (PMID 40341634, 2025).
atrial fibrillation (3 papers, 2016 to 2019). A disorder characterized by an electrocardiographic finding of a supraventricular arrhythmia characterized by the replacement of consistent P waves by rapid oscillations or fibrillatory waves that vary in size, shape and timing and are accompanied by an irregular ventricular response. "KCNIP1 (potassium voltage-gated channel interacting protein 1) is another example of a gene that could be linked by whole genome analysis to heart disease, here atrial fibrillation (AF)." (PMID 29911105, 2018).
glioblastoma (2 papers, 2019 to 2025). The most malignant astrocytic tumor (WHO grade IV). "Glioblastoma studies included E5 (KCNJ10, KCNN3), E21 (KCNAB2), E26 (KCNE2, KCNJ13), E27 (KCNE4, KCNMB2-AS1), E31 (KCNJ10), E50 (KCND3), and E51 (KCNIP1, KCNJ16, KCNN2)." (PMID 40867621, 2025).
Ataxia (1 paper, 2024). Ataxia refers to impaired coordination of voluntary muscle movement. "Interestingly, among the 24 PC genes with restored expression, seven genes (Abr, Calb1, Htr1b, Itpr1, Kcnip1, Kcnma1, and Mtss1) were part of a group of 80 PC-type-specific downregulated genes common to the SCA1, SCA2, and SCA7 mouse models and composed an ataxia molecular signature." (PMID 38673939, 2024).
cardiac hypertrophy (1 paper, 2012). "Prolongation of the cardiac action potential on the other hand, potentially caused by decreased Kcnip1 expression, is associated to cardiac hypertrophy." (PMID 22577878, 2012).
cervical cancer (1 paper, 2018). A primary or metastatic malignant neoplasm involving the cervix. "A set of key risk factors anaerococcus, hydrogenophilaceae, eubacterium, PSMB10, KCNIP1 and KRT13 have been identified, which are thought to be involved in the regulation of viral response, cell cycle and epithelial cell differentiation in cervical cancer." (PMID 29745858, 2018).
KCNIP1 also shares sentences with these, for which no sentence is quoted: bladder cancer (2 papers); cardiac arrhythmia (2); arteriosclerosis (1); attention deficit-hyperactivity disorder (1); behavioral anxiety (1); cancer (1); heart disease (1); Huntington disease (1); juvenile ALS (1); melanoma (1); mood disorder (1); neuroblastoma (1); neurodegenerative disease (1); neurodevelopmental disorder (1); tumor (1).